ALDOB (aldolase, fructose-bisphosphate B)
Diseases named in the same sentence as ALDOB in open-access papers (continued):
Sharing a sentence is not in itself a finding about the gene and the disease.
steatosis (3 papers, 2022 to 2023). Increased lipid within the cytoplasm of cells. "Upregulation of ALDOB in liver has been associated with steatosis in subjects with alcohol-related liver disease (ALD) and NAFLD." (PMID 36198307, 2022). "Fructose biphosphate aldolase B (ALDOB), a key enzyme in aldolase metabolism and a potential biomarker for NAFLD21, had the second highest correlation to steatosis (r = 0.41)." (PMID 35654907, 2022). "Consistently, and unlike aldolase B KO mice, which failed to thrive on ethanol, AldoB/Khk DKO mice had greater body weight gain with improved liver injury, as denoted by reduced inflammation, steatosis and overall, a significantly lower injury score and levels of transaminases ALT and AST in plasma." (PMID 37892451, 2023).
alcoholic liver diseases (2 papers, 2023 to 2025). A disorder caused by damage to the liver parenchyma due to alcohol consumption. "To determine the importance of endogenous fructose metabolism in alcoholic liver disease in aldolase B KO mice, we subsequently analyzed the response to ethanol of control aldolase B KO and AldoB/Khk DKO mice." (PMID 37892451, 2023).
bladder cancer (2 papers, 2018 to 2023). "On the other hand, ALDOB was highly expressed in urinary EV (mean Ct = 24.1 and median Ct = 23.9) and not differentially expressed among any diagnostic groups such as cancer type, bladder cancer stage and grade, therefore ALDOB was selected as a reference gene." (PMID 30214686, 2018). "Fructose bisphosphate aldolase B (ALDOB) was downregulated in the sEV fractions of bladder cancer patients in this study." (PMID 37371512, 2023). "Bladder cancer marker candidates as well as reference genes (ACTB, GAPDH, ALDOB) were assayed by RT-qPCR in 254 urine samples including 173 bladder cancer patient urine samples." (PMID 30214686, 2018). "Meanwhile, the most interesting proteins downregulated in the samples of bladder cancer patients were: collagen alpha-1 (VI) chain (COL6A1), fructose biphosphate aldolase B (ALDOB) and mannan-binding lectin serine protease (MASP2)." (PMID 37371512, 2023).
glioblastoma (2 papers, 2019 to 2025). The most malignant astrocytic tumor (WHO grade IV). "In contrast, aldolase A (ALDOA) and aldolase B (ALDOB) revealed no significant prognostic impacts in the glioblastoma cohorts." (PMID 31450822, 2019). "Unlike ALDOA and ALDOB, we observed that ALDOC inversely correlated with histology stages through heat map analysis of TCGA glioblastoma cohort (p < 0.0001, n = 538)." (PMID 31450822, 2019).
Hypoglycemia (2 papers, 2022 to 2024). A decreased concentration of glucose in the blood. "ALDOB deficiency in humans causes an accumulation of fructose-1-phosphate that subsequently leads to hypoglycemia." (PMID 39339686, 2024). "In humans, the absence of functional ALDOB enzyme due to mutations in the ALDOB gene cause hereditary fructose intolerance, characterized by metabolic disturbances that include hypoglycemia, lactic acidosis, and hypophosphatemia." (PMID 35230239, 2022).
melanoma (2 papers, 2014 to 2022). A malignant, usually aggressive tumor composed of atypical, neoplastic melanocytes. "It would be interesting to explore in future studies whether and how ALDOB and ALDOC are involved in melanoma cell invasion and survival." (PMID 24959248, 2014).
metastatic tumor (2 papers, 2021). "However, as the Gleason score and T stage increased, the expression of ALDOB was upregulated at a very low level, which might be particularly obvious in liver metastatic tumors, but it was still far below the level of expression in normal tissues." (PMID 34722497, 2021).
prostate carcinoma (2 papers, 2021 to 2025). A carcinoma that arises from epithelial cells of the prostate gland. "(2021) demonstrated that ALDOB functions as an autonomous predictor of metastasis-free survival in prostate cancer patients, exhibiting significant correlations with both pathological grading and tumor staging." (PMID 40852386, 2025). "By comparing the expression of ALDOB between normal prostate cells and prostate cancer cells, it was found that ALDOB was highly expressed in normal tissues, while ALDOB expression was very low in tumor tissues." (PMID 34722497, 2021). "In addition, the most important gene in the signature, ALDOB, was tested in vitro to verify the relationship between its expression and hypoxia and its effect on prostate cancer cells." (PMID 34722497, 2021). "The ALDOB gene, which contributed the most to the signature and was more sensitive to most medicines, was selected for in vitro experiments to verify its effect on prostate cancer cells under hypoxia." (PMID 34722497, 2021). "Based on the CellMiner database, the correlation analysis of commonly used therapeutic medicines for prostate cancer verified the therapeutic resistance of docetaxel, and the analysis showed that the medicines were sensitive to the ALDOB gene, especially oxaliplatin and teraplatin." (PMID 34722497, 2021).
renal cell carcinoma (2 papers, 2023 to 2026). "The literature review found that the detailed mechanism of ALDOB inhibiting the progression of renal cell carcinoma has been confirmed by other scientists." (PMID 36978048, 2023).
Sepsis (2 papers, 2021 to 2024). Sepsis is defined as life-threatening organ dysfunction caused by a dysregulated host response to infection. "Case NMA111, who was a 20-day-old female infant with hepatic dysfunction and suspected sepsis, had compound heterozygous variants in the gene ALDOB." (PMID 34733806, 2021).
type 2 diabetes (2 papers, 2023 to 2025). "Therefore, it will be important to investigate further how AldoB overexpression in islets of patients with type 2 diabetes affects beta cell AMPKα/mTOR activities, mitochondrial function, the dynamics of G3BP1+/INS mRNA condensates, and thus insulin production and secretion." (PMID 40355555, 2025). "Bioinformatic analysis of malonylated proteins and validation of fructose bisphosphate aldolase B (ALDOB) function reveals that glucose and lipid metabolism disorders in type 2 diabetes may be related to dysfunction of key enzymes resulting from aberrant PTM." (PMID 37833721, 2023).
breast carcinoma (1 paper, 2021). "Therefore, the higher expression of ALDOB in GATA3 mutant breast cancer tumors may be caused by involved common regulatory pathways that need to be confirmed by functional and gene–gene interaction analyses." (PMID 33462316, 2021).
cognitive decline (1 paper, 2022). "Thus, the omics data reveal that the reduced FBP1 and ALDOB and increased UQCRC2 can contribute to cognitive decline in T2DM patients through the mechanisms involving deregulated glucose metabolism and acidosis." (PMID 36506101, 2022).
colitis (1 paper, 2024). Inflammation of the colon. "Specifically, our results revealed decreased levels of glycolytic enzymes, including HK1, GPI, PFKL, ALDOA, and ALDOB in colitis." (PMID 38668322, 2024). "We observed a reduced relevant abundance for hexokinase (HK1), glucose-6-phosphateisomerase (GPI), phosphofructokinase (PFKL), fructose 1,6-biphosphate aldolase enzymes (ALDOA, ALDOB), triosephosphate isomerase (TPI), phosphoglycerate kinase 1 (PGK1), and alpha enolase (ENO1) in colitis." (PMID 38668322, 2024).
colorectal tumors (1 paper, 2015). "Thus, up-regulated expression was greater in PMP for SLC16A4, DSC3, ALDOB compared with colorectal tumors." (PMID 25929336, 2015).
lipodystrophy (1 paper, 2023). A congenital or acquired disorder characterized by abnormal loss or redistribution of the adipose tissue in the body. "ACOX1, ALDOB, protein kinase AMP-activated catalytic subunit alpha 2 (PRKAA2), JAK3, and protein tyrosine phosphatase non-receptor type 11 (PTPN11) have been confirmed to be closely related to β-oxidation of fatty acid, lipogenesis, cholesterol metabolism, and lipodystrophy." (PMID 36397714, 2023).
lymph node metastasis (1 paper, 2023). "Subsequent analysis revealed that ALDOB levels in GC tissues with lymph node metastasis (LNM) were decreased than in non-LNM GC tissues (P < 0.001), and were inversely associated with the tumor-node-metastasis (TNM) stage of GC patients (P < 0.001)." (PMID 37576390, 2023).
microtia (1 paper, 2024). "We hypothesize that reduced ALDOB protein levels in microtia patients may lead to decreased glycolysis and decreased MSC’s chondrogenic ability in some way which would be studied in future studies." (PMID 38802922, 2024). "The verification of the multi-omics results with other microtia patients identified that ALDOB, ADIPOQ, CDH13 and TASP1, and oxidative stress may play a role in chondrogenic anomalies." (PMID 38802922, 2024).
osteosarcoma (1 paper, 2014). A usually aggressive malignant bone-forming mesenchymal neoplasm, predominantly affecting adolescents and young adults. "ALDOA and ALDOB have been associated with poor prognosis of osteosarcoma and hepatocarcinoma, respectively." (PMID 24959248, 2014).
ovarian carcinoma (1 paper, 2023). A malignant neoplasm originating from the surface ovarian epithelium. "Similarly, our observations that single gene knockouts of ALDOB, ADH1B, NEU1, and NT5E block the metabolic alterations during both transitions concur with previous studies that show suppression of ovarian cancer growth upon silencing these genes." (PMID 37876796, 2023).
primary hyperoxaluria type 1 (1 paper, 2019). A rare disorder of glyoxylate metabolism characterized by the accumulation of oxalate due to a deficiency of the peroxisomal hepatic enzyme L-alanine: glyoxylate aminotransferase (AGT). "By literature reviewing, among the five genes, four have been well documented in HCC, including: ALDOB, IGFBP3, CYP2E1 and TOP2A, while AGXT was mostly studies in primary hyperoxaluria type 1, there are little reports of AGXT in HCC." (PMID 31771612, 2019). "Among the five genes, four (ALDOB; CYP2E1; IGFBP3; TOP2A) were well documented HCC related genes, while AGXT was mostly studies in primary hyperoxaluria type 1, but had not been reported in HCC." (PMID 31771612, 2019).
rectum adenocarcinoma (1 paper, 2025). An adenocarcinoma arising from the rectum. "Researchers found that elevated ALDOB expression exhibits strong links to clinical aspects of rectal adenocarcinomas, encompassing tumor progression and lymphovascular infiltration." (PMID 40852386, 2025).
renal carcinoma (1 paper, 2021). A carcinoma arising from the epithelium of the renal parenchyma or the renal pelvis. "The high expression of FBP1, ALDOB, LDHD, and SUCLA2 indicated a longer DFS and a low risk of developing renal cancer." (PMID 33564363, 2021). "The high expression of GPI, FBP1, ALDOB, and SUCLA2 indicated longer OS and a low risk of developing renal cancer." (PMID 33564363, 2021).
Renal cyst (1 paper, 2024). A fluid filled sac in the kidney. "The observed substantial downregulation of ALDOB (−233×) and upregulation of ALDOA (1.7×) further support increased glycolytic flux in renal cysts." (PMID 39000280, 2024).
ulcerative colitis (1 paper, 2015). An inflammatory bowel disease involving the mucosal surface of the large intestine and rectum. "Third was Aldolase B (ALDOB), an enzyme involved in fructose metabolism, which is known to be overexpressed in ulcerative colitis." (PMID 25929336, 2015).
ventricular septal defect (1 paper, 2024). The presence of a defect (opening) in the septum that separates the two ventricles of the heart. "For example, in humans, ALDOB (MIM: 612724) and MMP9 (MIM: 120361) have been found to be associated with ventricular septal defect." (PMID 38228144, 2024).
Zellweger syndrome (1 paper, 2020). "We observed a considerable decrease in KHK expression followed by ALDOB, both enzymes unique for fructose metabolism, on mRNA and protein levels in a Zellweger syndrome mouse model (Pex2–/– mice)." (PMID 32733884, 2020).
tumor (44 papers, 2015 to 2026). "This study aims to investigate the prognostic significance of ALDOB in ccRCC and its potential association with clinicopathological features and tumor immune microenvironment." (PMID 40852386, 2025). "A decrease in ALDOB expression is negatively associated with the presence of CD8+T cells in HCC tumor tissues, potentially allowing cancer cells to elude immune detection and affecting their susceptibility to immunotherapy." (PMID 40236649, 2025). "The analysis revealed a significant association between low ALDOB expression and overall survival (OS) in multiple tumor types, including COAD, KIRC, and LGG." (PMID 40852386, 2025). "ALDOB functions as a tumor suppressor, and its loss increases glycolysis while correlating with poor prognosis." (PMID 41220952, 2025). "In line with this, loss of the ALDOB gene (e.g., via copy number reduction) drives hyperactive glucose metabolism in metastatic ccRCC, promoting tumor progression and correlating with poor patient prognosis." (PMID 40520908, 2025). "The loss- and gain-of-function assessment demonstrated that ALDOB inhibited GC cells' capability to proliferate and migrate, suggesting its' anti-tumor activity in GC." (PMID 37576390, 2023). "Decreased ALDOB expression was associated with tumor invasion depth (χ2 = 5.918, P = 0.015), LNM (χ2 = 8.716, P = 0.003), and terminal stage of TNM (χ2 = 7.041, P = 0.008)." (PMID 37576390, 2023). "The overexpression of ALDOB in CRC is linked with tumor progression via transition of epithelial-mesenchyme and substandard prognosis." (PMID 37576390, 2023). "The assessment of loss- and gain-of-function indicated that ALDOB inhibited the growth and the migrative ability of GC cells, suggesting its anti-tumor role." (PMID 37576390, 2023). "Decreased ALDOB protein levels were associated with tumor size, high TNM stage, and shorter OS in our cohort." (PMID 36644641, 2022). "Overall, ALDOB appears to be implicated in the recruitment and regulation of tumor-infiltrating lymphocytes in ccRCC, warranting further investigation into its molecular mechanisms and impact on the tumor microenvironment." (PMID 40852386, 2025). "We discovered that patients with high tumor expression of ALDOB were associated with high levels of circulating CEA, prompting us to investigate whether CEACAM6 expression was correlated with ALDOB levels." (PMID 37816733, 2023). "Furthermore, ALDOB inhibition was notably linked with tumor size, depth of tumor invasion, lymph node metastasis (LNM), tumor node metastases (TNM) staging, and substandard prognosis of GC." (PMID 37576390, 2023). "In vivo validation confirmed icaritin suppressed tumor growth and M2 macrophage infiltration via the ALDOB/STX16/autophagy/STAT3 axis." (PMID 41731604, 2026). "Collectively, these findings suggest that ALDOB plays a crucial role across multiple cancer types, potentially through metabolic reprogramming within the tumor microenvironment." (PMID 40520908, 2025). "In conclusion, ALDOB's function in cancer encompasses both promotion of tumor growth and potential inhibition, revealing its complex involvement in oncogenesis and underscoring its importance as a therapeutic target." (PMID 40520908, 2025). "ALDOB also contributes to a pro-tumor metabolic microenvironment through enhanced lactate production and adaptation to hypoxia." (PMID 40520908, 2025). "Fructose enhances the expression of ALDOB by activating ChREBP and phosphorylating FoxO1/3α, potentially promoting vascular remodeling and tumor progression." (PMID 40520908, 2025). "Aldolase B (ALDOB), functioning as a glycolytic enzyme, exhibits a controversial role in malignancies and demonstrates dual potential as both a tumor suppressor and cancer-promoting enzyme." (PMID 40852386, 2025). "Parallel studies reveal miR-30-mediated ALDOB silencing across tumor contexts, linking its downregulation to pro-tumorigenic phenotypes including lipogenesis potentiation and apoptosis resistance." (PMID 40998906, 2025).
tumor (continued). "While the mechanisms by which ALDOB promotes tumor growth have been extensively discussed, research has also uncovered its potential role in cancer suppression." (PMID 40520908, 2025). "Ongoing investigations have examined ALDOB’s prognostic significance across diverse cancer types and explored its mechanistic contributions to tumor development." (PMID 40852386, 2025). "It appears that ALDOB is involved in tumor metastasis and progression, making it a potential diagnostic indicator of ccRCC." (PMID 40852386, 2025). "Classified into three groups (ALDOA, ALDOB, and ALDOC), ALDOA has been implicated in promoting tumor growth and metastasis in various cancers." (PMID 39765841, 2024). "Patients with higher ALDOB levels in their tumor tissue exhibited poorer therapeutic outcomes, suggesting that ALDOB expression affects the sensitivity of CRC cells to 5-FU or oxaliplatin." (PMID 37816733, 2023). "Aldolase B (ALDOB), as a glycolytic enzyme, plays a contentious role in cancers and can either act against the tumor or as an oncogenic enzyme." (PMID 37576390, 2023). "Corresponding to the protein level findings, patients with high ALDOB mRNA levels in tumor tissue (T > N) had an unfavorable prognosis." (PMID 37816733, 2023). "Patients with low ALDOB expression in tumor tissue (T ≤ N) were found to have a more favorable prognosis." (PMID 37816733, 2023). "Again, good prognosis was observed in patients with low ALDOB expression in tumor tissue (T ≤ N), suggesting that ALDOB expression sensitizes CRC to the anticancer agents 5-FU and oxaliplatin." (PMID 37816733, 2023). "Using the ratio of ALDOB levels in tumor and nontumor tissues, Kaplan–Meier analysis further confirmed that patients with high ALDOB expression in tumor tissue (T > N) had an unfavorable prognosis." (PMID 37816733, 2023). "Similar results were observed in tumor tissues derived from U87 cells with disruption of ATF4 binding motifs in the promoters of SLC2A5 or ALDOB." (PMID 36245009, 2022). "Generally, ALDOB is highly expressed in tumor samples; however, it appears as a protective factor in our analysis, signifying its role as a tumor suppressor in COAD." (PMID 36091047, 2022). "In general, ALDOB mRNA and protein levels were significantly downregulated and correlated with tumor size, TNM stage, SUVmax, and prognosis in HCC patients." (PMID 36644641, 2022). "A large cohort of 313 patients was analyzed, and ALDOB downregulation was reported to be significantly correlated with aggressive characteristics, increased tumor size (>5 cm), and shorter recurrence-free survival and OS." (PMID 36644641, 2022). "Among the identified genes, ALDOB was associated with a low risk, while five genes (GPC1, ALDOC, ENO2, SERPINE1, and SLC2A3) were associated with a high risk of developing tumor malignancy." (PMID 33737938, 2021). "ENO3, FBP1, FBP2, GPD1, and ALDOB were all glycolytic pathway-related proteins with inhibitory effects on tumor." (PMID 33200655, 2020). "It has been proposed that TUBA1C is associated with tumor cell death and cell proliferation, and aberrant expression of ALDOB contributes to tumor metastasis, which is involved in the initiation and development of HCC." (PMID 30344796, 2018). "Our previously acquired microarray data (GSE54238) showed downregulation of ALDOB in HCC as compared to normal liver or paired non-tumor tissue." (PMID 26376879, 2015). "Weekly tumor volume measurements showed the ALDOB overexpression group generated less number of tumors (5/8) compares to the controls (8/8)." (PMID 26376879, 2015). "In ccRCC, ALDOB has been identified as a metabolic tumor suppressor." (PMID 40520908, 2025). "Low ALDOB expression enhances glycolytic activity, contributing to tumor progression." (PMID 41220952, 2025). "In addition, tumor penetration depth, lymph node spread, distant metastasis, and tumor staging were closely correlated with ALDOB expression." (PMID 40852386, 2025).